HCLS1 (hematopoietic cell-specific Lyn substrate 1)
Description:
Substrate of the antigen receptor-coupled tyrosine kinase. Plays a role in antigen receptor signaling for both clonal expansion and deletion in lymphoid cells. May also be involved in the regulation of gene expression.
Synonyms: HS1; CTTNL; lckBP1; p75
Tractability: Antibody: UniProt places it where antibodies can reach, with high confidence; its Gene Ontology location is reachable by antibodies, with high confidence; the Human Protein Atlas places it where antibodies can reach. PROTAC: ubiquitination databases record sites on it; its protein half-life has been measured.
Gene: Protein-coding gene on chromosome 3 (121,631,399 to 121,660,927, reverse strand). Ensembl gene ENSG00000180353.
Subcellular location: Membrane; Cytoplasm; Mitochondrion
Subcellular location (Human Protein Atlas): Cytosol; Plasma membrane
Gene Ontology:
Molecular function: protein binding; protein kinase binding; RNA polymerase II-specific DNA-binding transcription factor binding; signaling adaptor activity; actin filament binding; protein-containing complex binding; SH3 domain binding
Biological process: actin filament organization; cellular response to cytokine stimulus; granulocyte colony-stimulating factor signaling pathway; negative regulation of leukocyte apoptotic process; nuclear transport; positive regulation of granulocyte differentiation; positive regulation of phosphatidylinositol 3-kinase/protein kinase B signal transduction; positive regulation of protein import into nucleus; positive regulation of transcription by RNA polymerase II; regulation of actin filament polymerization; erythrocyte differentiation; intracellular signal transduction; positive regulation of cell population proliferation; regulation of DNA-templated transcription; response to hormone; signal transduction; negative regulation of transcription by RNA polymerase II; positive regulation of macrophage differentiation
Cellular component: cytoplasm; cytosol; nucleus; plasma membrane; transcription regulator complex; endocytic vesicle; membrane; mitochondrion
Genetic constraint (gnomAD): Loss-of-function variants: 27 observed, 49.81 expected, observed/expected ratio (o/e) 0.54, 90% interval 0.4 to 0.75. The upper end of that interval is the gene's LOEUF score, 0.75, which puts it in group 3 of 6, group 1 being the genes least tolerant of losing a copy. Missense variants: 513 observed, 548.85 expected, observed/expected ratio (o/e) 0.93, 90% interval 0.87 to 1. Synonymous variants: 196 observed, 206.78 expected, observed/expected ratio (o/e) 0.95, 90% interval 0.84 to 1.07.
Homologues: Orthologues: chimpanzee HCLS1 (99% identical), macaque HCLS1 (93% identical), pig HCLS1 (86% identical), rabbit HCLS1 (85% identical), dog HCLS1 (85% identical), guinea pig HCLS1 (84% identical), rat Hcls1 (83% identical), mouse Hcls1 (82% identical), zebrafish hcls1 (52% identical), tropical clawed frog hcls1 (49% identical). Paralogues in human: CTTN (47% identical), DBNL (18% identical), DBN1 (16% identical), COTL1 (5% identical).
Diseases named in the same sentence as HCLS1 in open-access papers:
HCLS1 is named in the same sentence as 29 diseases in open-access papers, as found by Europe PMC text mining. Sharing a sentence is not in itself a finding about the gene and the disease. The quoted sentences say what the papers report.
chronic lymphocytic leukemia (3 papers, 2020 to 2024). "Levels of HCLS1 were linked to chronic lymphocytic leukemia, though its role in cancers, particularly OS, remains unclear." (PMID 39108264, 2024). "HCLS1 is expressed mainly in hematopoietic cells, which regulates the migration of leukemic cells and may be a promising target for the treatment of chronic lymphocytic leukemia." (PMID 33042828, 2020). "Among them, studies have shown that HCLS1 might be a potential therapeutic target gene of chronic lymphocytic leukemia." (PMID 32426282, 2020).
osteosarcoma (3 papers, 2015 to 2023). A usually aggressive malignant bone-forming mesenchymal neoplasm, predominantly affecting adolescents and young adults. "HCLS1 has been found to be associated with clinical prognosis and immune-correlation in osteosarcoma." (PMID 37274231, 2023). "Hematopoietic cell specific Lyn substrate 1 (HLCS1) was differentially expressed (fold change 0.25, P value 0.0005) between MSCs of osteosarcoma patients (n = 14) and healthy donors (n = 9)." (PMID 26106474, 2015).
breast carcinoma (2 papers, 2020 to 2023). "Knockdown of hCLS1 in hCMEC/D3 reduced CL and the mRNA expression of creatine transporter-1, p-glycoprotein and breast cancer resistance protein compared to controls." (PMID 40084065, 2023).
colorectal cancer (2 papers, 2015 to 2025). A primary or metastatic malignant neoplasm that affects the colon or rectum. "Moreover, the relationship between HCLS1 and HCC has rarely been reported, although it was negatively correlated with the OS of patients with colorectal cancer." (PMID 40357287, 2025).
adenoma (1 paper, 2025). A neoplasm arising from the epithelium. "Specifically, GBP2 and P2RX7 were significantly downregulated in both the “Adenomas and Adenocarcinomas” subtype and the “Cystic, Mucinous and Serous Neoplasms” subtype (p < 0.001), while SLC11A1 and HCLS1 were significantly upregulated in these two subtypes (p < 0.01)." (PMID 41007849, 2025).
asthma (1 paper, 2025). "Analysis of tight‐junction gene sets revealed the reduced expression of a whole cluster of genes such as OCLN, CLDN3, CLDN4, NRAS, HCLS1, MYH10 in virus‐infected cells from patients with asthma in comparison to the controls." (PMID 39466641, 2025).
COVID-19 (1 paper, 2022). A disease caused by infection with severe acute respiratory syndrome coronavirus 2. "The proteins overlapping with the enriched “B-cell Receptor Signaling Pathway (WP23),” JUN, HCLS1, PIK3AP1, and CRKL, were all increased in abundance in the COVID-19 spleen tissue, in addition to IL-18R1." (PMID 34710339, 2022).
escherichia coli infection (1 paper, 2020). Infection with the organism Escherichia Coli. "Analysis on the basis of the KEGG revealed HCLS1 and TUBA4A to be enriched for Pathogenic Escherichia coli infection (hsa05130; 2/53) and Tight junction (hsa04530; 2/167)." (PMID 32371984, 2020). "In line with this concept, KEGG enrichment revealed HCLS1 and TUBA4A to be enriched for Pathogenic Escherichia coli infection (hsa05130; 2/53) and Tight junction (hsa04530; 2/167)." (PMID 32371984, 2020).
latent infection (1 paper, 2019). "Here, we now show that, subsequent to virus binding and in response to the latency-associated upregulation of HCLS1, latent infection of monocytes results in increased stability of filamentous actin, which, in turn, enhances monocyte migration." (PMID 31569051, 2019). "In contrast, lytic infection of monocyte-derived DCs showed only a minor increase in HCLS1 over already high background levels of HCLS1 and argues that the most profound functional effects of HCLS1 induction are likely to be during latent infection." (PMID 31569051, 2019). "Taken together, these data argue that latent infection of CD14+ monocytes results in increased levels of cellular HCLS1, which stabilizes actin filaments and concomitantly results in enhanced monocyte motility." (PMID 31569051, 2019). "Taken together, these data suggest that latent infection of monocytes results in a substantial increase in HCLS1, which is, at least in part, mediated by US28." (PMID 31569051, 2019). "We found that, in contrast to latent infection, lytic infection of DCs resulted in only minor increases in HCLS1, over an already high basal level of HCLS1 expression and that US28 likely played only a minor role in this upregulation." (PMID 31569051, 2019). "This confirmed that HCLS1 is substantially increased during latent infection at both the protein (western blot) and mRNA (RT-qPCR) levels, but not in response to UV-inactivated virus." (PMID 31569051, 2019). "We next addressed the potential role of HCLS1 induction during latent infection." (PMID 31569051, 2019). "Further analysis of these data identified that one of the most highly upregulated proteins associated with latent infection was HCLS1, which was not upregulated following infection with a UV-inactivated virus." (PMID 31569051, 2019). "Consequently, we believe that the most profound functional effects of HCLS1 induction are likely to be during latent infection." (PMID 31569051, 2019). "Therefore, we validated this upregulation of HCLS-1 during latent infection." (PMID 31569051, 2019).
metastatic melanoma (1 paper, 2025). A melanoma that has spread from its primary site to another anatomic site. "In addition, BIN2, CMTM8, CXCL10, HCLS1, ITGB2, PTPN2, and RFTN2 were expressed at significantly higher levels in our B16 brain-derived variants compared with the parent B16-F0 and are also upregulated in human metastatic melanomas compared with primary cutaneous tumors." (PMID 39819494, 2025).
myocardial infarction (1 paper, 2025). Gross necrosis of the myocardium, as a result of interruption of the blood supply to the area, as in coronary thrombosis. "Importantly, validation in a murine myocardial infarction (MI) model further corroborated these observations, demonstrating significant upregulation of TIMP1 and THBS4 mRNA expression, alongside downregulation of HCLS1." (PMID 41393260, 2025).
viral infection (1 paper, 2023). "IFIT5 is a factor in HCV entry, HCLS1 is a newly identified transcription regulator, and RSAD2 and IFIT5 are ISGs that have been shown to be critically important to resistance to viral infection, including influenza virus, HIV-1, and other viruses." (PMID 37896995, 2023).
cancer (10 papers, 2019 to 2025). A tumor composed of atypical neoplastic, often pleomorphic cells that invade other tissues. "A high expression level of HCLS1 in B-cell-derived malignant tumors was observed to be related to poor prognosis." (PMID 40357287, 2025). "In the osteoblasts_Gapd2 subpopulation, pathways such as proteoglycans in cancer (Col1a1, Col1a2, Hcls1, Hif1a, Stat3, Vav1), IL-17 signaling (Mmp13, Mmp3, S100a9, Ccl7, Cebpb), and ECM–receptor interaction (Col11a2, Col1a1, Ibsp, and Tnn) were activated (p < 0.05)." (PMID 41459160, 2025). "HCLS1 controls the process of cellular viability, migration, and cancer progression." (PMID 41007849, 2025). "As a result, using Onco Query Language (OQL) EXP > 2, in proteoglycans in cancer signaling pathway, two targets EZR and HCLS1 were found to be negatively correlated with overall survival (OS) (P = 4.94E-4 and 0.011)." (PMID 32293320, 2020). "Seven target genes, namely DDX5, SOS2, ACTG1, EZR, FN1, HCLS1 and PIK3R5, were involved in proteoglycans in cancer signaling pathway." (PMID 32293320, 2020). "After systemic analysis of prognosis-related miRNA targets in those cancer-related signal pathways, we found that two targets ezrin (EZR) and hematopoietic cell-specific Lyn substrate 1 (HCLS1) had the potential prognostic characteristics with CRC regarding over survival (OS) or recurrence." (PMID 32293320, 2020). "When comparing our gene expression analyses and genetic analyses, the cancer genes HLA-DPA1, HLA-DMB, DNAJA4, LY86, HCLS1, GABBR1, NUDT16 showed upregulation in tumor tissue compared to cell subpopulations and are located in chromosomal regions that showed losses in GSC and CD133pos./CD15pos. cells." (PMID 32634135, 2020). "Although SLC11A1 shows excellent immunological prognostic value in other cancers, our K-M curves show better survival for high-expression groups of GBP2, P2RX7, and HCLS1 but not SLC11A1 in EC." (PMID 41007849, 2025).
tumor (10 papers, 2011 to 2025). "The results showed that two cortactin-encoding genes, CTTN and HCLS1, were markedly increased in tumor tissues." (PMID 35178403, 2021). "Further studies are needed to determine if HCLS1 might have a tumor suppressor function and if its loss of expression in OS patients derived MSCs has any relationship to in vivo tumorigenesis." (PMID 26106474, 2015). "There were substantial differences in CpG methylation in GBP2, SLC11A1, and HCLS1 between tumor and normal samples." (PMID 41007849, 2025). "Three of these, i.e., Lrmp, Hcls1 and Prkrir, were up regulated and one, i.e., Ptp4a3, was down regulated in the affected tumor." (PMID 22028901, 2011). "This suggests that HCLS1 may influence EC progression by affecting tumor cell proliferation and metastasis." (PMID 41007849, 2025). "HCLS1 may have a similar function to P2RX7 by affecting tumor cell proliferation and metastasis." (PMID 41007849, 2025). "The results of immunochemistry showed that GBP2, HCLS1, P2RX7, and SLC11A1 were more highly expressed in the tumor group than in the normal group." (PMID 41007849, 2025). "We also studied the effects of HCLS1, CORO1A and CCRL2 on tumor metastasis-related indicators at the cellular level through in vitro experiments." (PMID 37274231, 2023). "Further, our data from the functional study confirmed that the overexpression of HCLS1, EVI2B, and CD48 can reduce the ability of proliferation, migration, and invasion in CRC cells and significantly suppress CRC tumor growth in vivo." (PMID 32426282, 2020). "Further, the functional study verified that over-expression of HCLS1, EVI2B, and CD48 can reduce the proliferation, migration, and invasion ability of CRC cells and significantly suppress CRC tumor growth in vivo." (PMID 32426282, 2020). "Our data from the functional study confirmed that HCLS1, EVI2B, or CD48 suppresses CRC progression by inhibiting the proliferation, migration, and invasion capacity of CRC cells as well as tumor growth in vivo." (PMID 32426282, 2020). "The immunostaining revealed that HCLS1, EVI2B, or CD48 proteins expression were higher in pcDNA 3.3-HCLS1, pcDNA 3.3-EVI2B, or pcDNA 3.3-CD48 compared with pcDNA 3.3-NC group in xenografted tumor." (PMID 32426282, 2020). "Furthermore, the functional study confirmed that the overexpression of HCLS1, EVI2B, and CD48 can reduce the proliferation, migration and invasion ability of CRC cells in vitro and significantly suppress CRC tumor growth in vivo." (PMID 32426282, 2020). "Similarly, the expression of BTN3A1, CSF2RB, GIMAP7, GZMB, HCLS1, LCP2, and SELL was positively correlated with the infiltration of B cells, CD8+ T cells, CD4+ T cells, neutrophil, and DCs, but was negatively correlated with the tumor purity." (PMID 33042828, 2020).
infection (4 papers, 2015 to 2025). The state of being infected such as from the introduction of a foreign agent such as serum, vaccine, antigenic substance or organism. "Instead, RSFR, MPEG1, ITGLB2 and HCLS1 were suppressed in HD11 cells 24 h after infection with wild type S. Enteritidis." (PMID 26380970, 2015). "Consequently, lytic infection of DCs results in only a small increase in HCLS1 over an already high basal level of HCLS1 expression in these cells, and this small increase is only partially US28 dependent." (PMID 31569051, 2019). "One transcription factor that was predicted to bind to the HCLS1 promoter was ATF1, and this particularly came to our attention because it is known to be upregulated by Src signaling, a signaling pathway known to be involved in infection of monocytes by HCMV." (PMID 31569051, 2019). "As Src phosphorylation has also been published as an effect of US28 during lytic infection, we also addressed whether US28 can mediate HCLS1 upregulation during lytic infection." (PMID 31569051, 2019). "As US28 is also known to target Src phosphorylation during lytic infection, we tested whether US28 could also mediate HCLS1 upregulation during a lytic infection." (PMID 31569051, 2019).
HCLS1 also shares sentences with these, for which no sentence is quoted: bacterial infections (2 papers); congenital neutropenia (2); melanoma (2); adenocarcinoma (1); brain tumors (1); endometrial carcinoma (1); Kostmann’s disease (1); leukemia (1); pancreatic cancer (1); periodontitis (1); primary immunodeficiency (1); staphylococcus aureus infection (1); systemic lupus erythematosus (1); type 1 diabetes mellitus (1).